ZEB1 (zinc finger E-box binding homeobox 1)
Diseases named in the same sentence as ZEB1 in open-access papers (continued):
Sharing a sentence is not in itself a finding about the gene and the disease.
glioma (continued). "Co-culture of mast cells with glioma cells induces the expression of serglycin, CD44, ZEB1, vimentin, CXCL10, CXCL12, and TNF-α in glioma cells and IL-6 and CXCL1 in mast cells, creating an inflammatory milieu that induce glioma cell aggressiveness." (PMID 35494005, 2022). "Immunohistochemical staining revealed that five genes (ZEB1, CA9, HSPb1, STAT3, and TNFAIP3) had a higher expression in glioma tissues than in normal tissues." (PMID 35711838, 2022). "LncRNA HOXC-AS2 formed a positive feedback loop with ZEB1 through miR-876-5p to regulate the EMT in glioma, providing a potential therapeutic target for glioma prevention." (PMID 35912271, 2022). "In summary, OR7E156P/miR-143 axis regulates HIF-1α downstream ZEB1, and VEGF signaling pathways, affecting glioma cell invasion." (PMID 34422645, 2021). "Consistently, miR-143 knockdown within glioma cells dramatically reversed the roles of OR7E156P knockdown in HIF1A, ZEB1, and VEGF expression." (PMID 34422645, 2021). "These biological behavior changes in glioma cells were dependent on the binding to potential target genes including CDK6 and ZEB1." (PMID 34796112, 2021). "ZEB1 levels were inversely correlated with TET2 levels in tumors, and physical binding of ZEB1 to the TET2 promoter in glioma cells was observed in vitro." (PMID 33842321, 2021). "In glioma, HOXA transcript at the distal tip induces the expression of zinc finger E-box-binding homeobox 1 and promotes EMT by sponging miR-101 under hypoxic conditions." (PMID 31477638, 2019). "Expression of ZEB1 and ZEB2 was significantly increased in glioma tissues compared with normal tissues." (PMID 31429770, 2019). "We chose four mesenchymal transition markers (N-cadherin, ZEB1, Slug, and CD44) from the gene list identified by GSEA, which are reported to be involved in glioma mesenchymal transition, and analyzed the relationship between these markers and PBX3 expression." (PMID 30016974, 2018). "Specifically, accumulation of nuclear ZEB1 was correlated with enhanced expression of two mesenchymal markers, collagen 5A1 (COL5A1) and fibronectin, as well as elevated invasive potential of glioma cells both in vitro and in vivo." (PMID 28821904, 2018). "In conclusion, these findings indicate the importance of infiltrating MCs in glioma by modulating signaling cascades involving serglycin, CD44 and ZEB1." (PMID 28445977, 2017). "Analysis of TCGA data for copy number along with expression data where we correlated expression and copy number data, revealed a significant decrease in ZEB1 expression in both GBM and low grade glioma patients (P < 0.0001 and P = 0.0006 respectively)." (PMID 28246407, 2017). "LOH of chromosome 10 occurs only in GBMs while LOH of ZEB1 occurs in both GBM and lower grade gliomas." (PMID 28246407, 2017). "Here, we found that ING5 up-regulated the Claudin 1 expression, but down-regulated the expression of N-cadherin, Slug, Snail, Twist, Zeb1 and Zeb2, indicating that ING5 suppressed the EMT in glioma." (PMID 28915612, 2017). "ZEB1, a member of the zinc-finger E-box-binding homeobox (ZEB) protein family, is a core factor responsible for mediating EMT in numerous cancer types, including glioma." (PMID 28388562, 2017).
glioma (continued). "KITENIN induced the expression of the epithelial-mesenchymal transition (EMT) markers (N-cadherin, ZEB1, ZEB2, SNAIL and SLUG) as well as the glioma stemness markers (CD133, ALDH1 and EPH-B1)." (PMID 25605251, 2015). "ZEB1, an EMT inducer, was recently shown to be key in linking glioma stemness, invasiveness, and the expression of the chemoresistant enzyme O-6-methylguanine DNA methyltransferase (MGMT)." (PMID 25605251, 2015). "Several EMT markers or inducers, including Twist1, ZEB1, and SNAIL, have been reported to enhance glioma stemness, leading to cancer progression and therapeutic resistance." (PMID 25605251, 2015). "Under hypoxic conditions, knockdown of ZEB1 in glioma cells significantly reduces their invasiveness, with no major changes observed in stromal markers." (PMID 41141394, 2026). "NOTCH1, SOX2, TJP1/ZO1, ZEB1, and ZEB2 have higher expression in lower-grade glioma vs GBM." (PMID 40679044, 2025). "By upregulating zinc finger E-box binding homeobox 1 (ZEB1), UCA1 could sponge miR-204-5p to stimulate glioma cell motility, invasion, and EMT." (PMID 39170516, 2024). "Here, we report a similar signature whereby TWEAK-induced p52 activity resulted in the increased enrichment of oncogenic motifs, such as various ETS factors, KAISO and ZEB1, at ETS1 binding sites and augmented genome-wide ETS1 DNA binding, which altered the transcriptomic landscape of gliomas." (PMID 37087499, 2023). "Here, ZEB1 is a transcription factor that mediates EMT in a variety of tumors, including gliomas." (PMID 37240419, 2023). "Our results revealed that quercetin decreased the expression of ZEB1 and this effect could be rescued by SB216763, implying that quercetin decreases ZEB1 expression via GSK-3β/β-catenin axis in glioma." (PMID 36386155, 2022). "Moreover, ZEB1, CA9, HSPB1, STAT3 and TNFAIP3 of the overlapping genes were upregulated in glioma tissues." (PMID 35711838, 2022). "In summary, our data revealed that knockdown of H19 may suppress the development of glioma in vivo by up-regulating miR-200a and down-regulating CDK6/ZEB1." (PMID 34796112, 2021). "In summary, our findings suggested that the expression of H19 was elevated in glioma, which could promote the growth, invasion and migration of tumor cells via H19/miR-200a/CDK6/ZEB1 axis." (PMID 34796112, 2021). "Altogether, a regulatory axis consisting of OR7E156P, miR-143, and HIF1A, which is deregulated in glioma was identified, and the process of the OR7E156P/miR-143/HIF1A axis modulating glioma cell invasion through ZEB1 and HUVEC tube formation through VEGF was ascertained." (PMID 34422645, 2021). "TIME cluster A exhibited the high expression profiles of ZEB1, TNF, and LAG3; while GZMA, CXCL9, CXCL10, and CD8A were relatively overexpressed in TIME cluster C. EMT is a common process of paramount importance in glioma occurrence and invasion." (PMID 34650972, 2021). "Similarly, transcription-factor regulators (e.g., ZEB1) and enhancers (e.g., TNC) of invasion were significantly increased both in human ATRX-mutant and ATRX-KO murine glioma specimens." (PMID 34763709, 2021). "Knockdown of H19 could induce the biological behavior changes of glioma cells by up-regulating miR-200a and down-regulating CDK6/ZEB1." (PMID 34796112, 2021). "Whereas ZEB1 and ZEB2 expression were highly expressed in low-grade, IDH-Mutant, 1p19q codel and younger glioma patients, indicating that the potential function of these genes in glioma malignancies." (PMID 32154177, 2020). "Transfection of RIOK2 siRNAs significantly inhibited glioma cell migration and invasion and down‐regulated the expression of MMPs (MMP2 and MMP9) and mesenchymal markers (N‐cadherin, β‐catenin, Twist1, fibronectin, ZEB‐1) in glioma cells." (PMID 32125767, 2020). "In addition, TGF-β induces the expression of the transcription factor zinc-finger E-box binding homeobox 1 (ZEB1), which is involved in EMT transition in gliomas." (PMID 32019108, 2020).
glioma (continued). "In addition, with the advent of IDH status in gliomas it would be interesting to see how incorporation of both IDH and ZEB1 would benefit patients." (PMID 30705664, 2018). "In particular, miR-139-5p suppresses cancer cell migration by targeting ZEB1 and ZEB2 in glioma." (PMID 30170559, 2018). "Further, no pattern appears to exist regarding where ZEB1 expression is found within gliomas (both and high and low grade) within the brain that can be attributed to tumor suppressor or oncogenic activity." (PMID 32309604, 2018). "As microglia and tumor-associated macrophages have been shown to account for up to 30% of cells in glioma, they can thus substantially contribute to the ZEB1-negative population." (PMID 28945795, 2017). "Our study clearly shows that an EMT-like transition is obtained by fibronectin-dependent activation of α5β1 integrin in glioma cells as known EMT activators (snail, zeb1) or markers (vim) are increased under the control of beta-catenin and decreased by the integrin antagonist K34c." (PMID 27613837, 2016). "In our study, we found that blocking the expression of RACK1 greatly inhibited migration and invasion ability of glioma cells, and discovered that knockdown of RACK1 significantly decreased the expression of EMT markers, such as MMP2 and MMP9, ZEB1, N-cadherin, and Integrin-β1." (PMID 27763568, 2016). "CTGF was also found to play a prominent role in glioma cell invasion by activating ITGB1-TrkA-NFkB axis, wherein it resulted in the activation of ZEB-1 (a transcriptional repressor), which subsequently brought down the levels of e-cadherin and thereby enhanced migration and invasion." (PMID 27291091, 2016). "Let-7 also targets pre-B-cell leukemia homeobox 3 (PBX3) in glioma, a protein which mediates transforming growth factor β (TGF-β) signaling, driving the expression of genes that increase migration—N-cadherin (N-cad), zinc finger E-box-binding homeobox 1 (ZEB1), SNAI2, and CD44." (PMID 37370851, 2023). "Thus, an increase in the level of ZEB1 mRNA does not necessarily lead to the common and large-scale activation of ZEB1-dependent genes in glioma cells." (PMID 36231068, 2022). "However, the biological effects of H19, miR-200a, CDK6 and ZEB1 as well as their interaction in glioma has not been elucidated." (PMID 34796112, 2021). "The results showed that the mRNA expression levels of Twist1, Twist2, Zeb1, Zeb2 and Slug2 maintained significantly negative correlations with the mRNA expression levels of Presenilin1 in gliomas of all WHO grades, but the relationships were not significant between Presenilin1 and Slug1." (PMID 34781973, 2021). "In addition, by using GEPIA web tool, the up-regulation of ZEB1 was further confirmed in glioma samples (GBM) compared to noncancerous tissues (Tumor=163, Normal=207, p<0.05)." (PMID 34796112, 2021). "Interestingly, ZEB1, the most expressed EMT regulator across our BTSC lines, plays central roles in regulating differentiation and invasion in both NSCs during development and glioma cells." (PMID 31652994, 2019). "HOTTIP was aberrantly down-regulated in glioma, and over-expression of HOTTIP inhibited the growth of glioma in vitro and in vivo by regulation of BRE (brain and reproductive) gene expression, besides, HOTTIP promotes hypoxia-induced EMT of malignant glioma by regulating the miR-101/ZEB1 axis." (PMID 30376874, 2018).
glioma (continued). "In contrast, glioma cell lines constitutively express ZEB1 irrespective of gene expression subtype." (PMID 28945795, 2017). "In contrast to glioma stem cells, U87 cells showed no overexpression of stem cell markers, such as SOX2, ZEB1, ATXN1, ALCAM, CD9, ITGA7, CD44 and CHI3L1." (PMID 34680293, 2021). "TCGA database analysis showed that ZEB1, ZEB2 and TWIST1 expression, but not E-Cadherin, were increased in glioma." (PMID 31429770, 2019). "The expression of ZEB1 and vimentin as well as Ki-67 (MKI67) as proliferation marker, was increased in co-cultured glioma cells as compared to glioma cells cultured without LAD2 cells." (PMID 28445977, 2017).
lung adenocarcinoma (76 papers, 2012 to 2026). A carcinoma that arises from the lung and is characterized by the presence of malignant glandular epithelial cells. "Next, we moved to investigate the underlying mechanism of ZEB1 downregulation by Biochanin A in lung adenocarcinoma." (PMID 36512117, 2022). "Through this epigenetic regulation by histone lysine modification, Slug, Twist, and ZEB1 is likely associated with longer survival in patients with BM of lung adenocarcinoma." (PMID 33291558, 2020). "Collectively, these results suggest that EGFR mutations correlate with the loss of ZEB1 in lung adenocarcinomas." (PMID 27456471, 2016). "Another study also indicated that TTN-AS1 enhanced tumor invasion and migration by targeting the miR-4677-3p/ZEB1 axis in lung adenocarcinoma." (PMID 41602333, 2026). "In lung adenocarcinoma, miR-1236 negatively correlates with Zinc finger E-box binding homeobox 1 (ZEB1)." (PMID 41009512, 2025). "On the other hand, DNMT3Aa induces malignant transformation of lung adenocarcinoma cells by induction of the level of HDAC7 with concomitant increase of ZEB1 and c-Myc." (PMID 40764968, 2025). "The involvement of the miR-200/ZEB1 axis was further examined in lung adenocarcinoma metastasis, and it was found it was discovered that ZEB1-induced decreases in miR-200 increase tumor cell invasion and metastasis." (PMID 39343796, 2024). "Our findings elucidate the roles played by FBXO11 and ZEB1 in lung adenocarcinoma from a fundamental molecular perspective." (PMID 39409891, 2024). "Low FBXO11 expression in lung adenocarcinoma cells increases ZEB1 protein levels, decreases epithelial marker E-cadherin, and increases mesenchymal markers N-cadherin and vimentin, promoting EMT and enhancing cell migration and invasion." (PMID 39409891, 2024). "The transcription factor ZEB1 plays a fundamental role in CAF heterogeneity induced by cancer cell contextual cues, particularly in lung adenocarcinoma (LUAD) where ZEB1-overexpressing tumor cells can reprogram CAFs through a ZEB1-dependent secretory program." (PMID 38124183, 2023). "In this study, our results further demonstrated that inhibition of ZEB1 expression by Biochanin A significantly enhances the sensitivity of lung adenocarcinoma cells to cisplatin in vitro and in vivo." (PMID 36512117, 2022). "In conclusion, we have demonstrated an alternative role of Biochanin A in regulating lung adenocarcinoma cell proliferation and metastasis that supplements the deubiquitination and stabilization of ZEB1." (PMID 36512117, 2022). "At the molecular level, Biochanin A affects the stability of ZEB1 protein through the deubiquitination pathway and thereby influences the progression of lung adenocarcinoma." (PMID 36512117, 2022). "hsa-miR-33b-5p can attenuate EMT of tumor cells by targeting the modulation of ZEB1 in lung adenocarcinoma." (PMID 33397428, 2021). "The expression of ATG5 and Zeb1 were both positively correlated with the stage of human lung adenocarcinoma." (PMID 33468994, 2021). "Analyses based on clinical specimens showed that AHNAK2 regulated the EMT via a TGF-β/Smad3 pathway in lung adenocarcinoma and a hypoxia inducible factor-1α/zinc finger E-box-binding homeobox 1 (HIF-1/ZEB1) pathway in clear cell renal cell carcinoma." (PMID 33918555, 2021). "The clinical relevance of the relationship between autophagy and Zeb1 was evaluated in human lung adenocarcinoma using clinical TCGA datasets." (PMID 33468994, 2021). "In the present study, we show an inverse correlation of AGR2 with ZEB1 (zinc finger enhancer binding protein, δEF1) that was verified by analysis of several independent clinical data sets of lung adenocarcinomas." (PMID 32570918, 2020). "The other study indicated that circ-TSPAN4 facilitates lung adenocarcinoma metastasis by elevating ZEB1 via sponging miR-665." (PMID 33195693, 2020).